INS (insulin)
Diseases named in the same sentence as INS in open-access papers (continued):
Sharing a sentence is not in itself a finding about the gene and the disease.
type 2 diabetes (continued). "Pancreatic β-cells are key players in the body’s insulin homeostasis and, when subjected to stress, can lose function and lead to type 1 and type 2 diabetes." (PMID 37759604, 2023). "The addition of these agents also enabled a proportion of patients with type 2 diabetes on multiple daily injections to discontinue prandial insulin: 42% of patients on prandial insulin discontinued it by 3 months following GLP1 RA initiation." (PMID 37589043, 2023). "The CIMT trial evaluated the effect of an 18-month treatment with metformin versus placebo and simultaneously the effect of three insulin analogue regimens on the progression of mean carotid intima media thickness in patients with type 2 diabetes." (PMID 36923108, 2023). "Regular physical activity is a powerful regulator of metabolic health, and it is well known to improve glucose tolerance and insulin sensitivity in individuals with obesity and type 2 diabetes." (PMID 37064893, 2023). "Pioglitazone (PIO) improves the sensitivity of peripheral tissues to insulin, controls glycemia, dyslipidemia and hypertension, and also reduces albuminuria in patients with type 2 diabetes." (PMID 38276837, 2023). "GLP-1 also reduced NEFAs in fasting hyperglycaemic individuals with type 2 diabetes, mainly during the period when insulin concentrations were elevated owing to the insulinotropic action of GLP-1." (PMID 37430117, 2023). "In type 2 diabetes, insulin resistance drives beta cells to secrete more insulin to meet the physiological requirements." (PMID 37843554, 2023). "Type 2 diabetes mellitus (T2DM) occurs when the body is unable to preserve normal glucose levels due to insulin resistance and β-cell dysfunction." (PMID 37888077, 2023). "Type 2 diabetes is often managed with lifestyle modifications, oral medications, and, in some cases, insulin therapy." (PMID 38022307, 2023). "In type 2 diabetes, glucokinase activity is decreased, leading to a decrease in insulin secretion and hyperglycemia." (PMID 37240215, 2023). "Lysine has also been reported to be insulinotropic and positively correlated with glucagon-like peptide-1 (GLP-1) in patients with type 2 diabetes, adding to the explicably lower breakfast glycemic excursions through greater precursor and insulin signaling." (PMID 37110149, 2023). "Higher circulating levels of TGF-β are related to obesity with impaired insulin sensitivity, cardiovascular diseases, type II diabetes, and old age." (PMID 36901121, 2023). "Type 2 diabetes mellitus (T2DM) is a progressive metabolic condition characterised by insulin resistance and pancreatic B-cell dysfunction, resulting in hyperglycaemia." (PMID 37892437, 2023). "PPARγ agonists, TZDs, are sensitize cells to insulin and improve insulin sensitivity to treat type 2 diabetes." (PMID 37427406, 2023). "All the patients were diagnosed with type 2 diabetes before hospitalization, and most patients in both groups were being treated with non-insulin antidiabetic medications (53.3% vs. 70%)." (PMID 37736430, 2023). "The present study aimed to evaluate the impact of isCGM devices versus CBG on the glycemic control of inpatient type 2 diabetes on intensive insulin therapy." (PMID 37736430, 2023). "The OGTT is a recognized tool used in the diagnosis of type 2 diabetes that is frequently used to measure insulin resistance." (PMID 37372530, 2023). "The ability to increase insulin secretion through the incretin effect of DPP-4 inhibitors has been described not only in type 2 diabetes but also in CFRD." (PMID 37371849, 2023). "These constituents were found to target a variety of aberrant carbohydrate metabolic pathways, resulting in a reduction in blood glucose and insulin levels in type 2 diabetics." (PMID 36985818, 2023). "Ophiopogon japonicus extract can significantly lower blood glucose levels on experimental type 2 diabetic rats by improving insulin sensitivity and increasing glycogen contents in liver and skeletal muscle." (PMID 36967788, 2023).
type 2 diabetes (continued). "Treatment for Type 1 diabetes involves insulin injections, while the management of Type 2 diabetes includes lifestyle modifications, dietary changes, and oral anti-diabetic medications to enhance insulin sensitivity." (PMID 37504903, 2023). "The injection of sesamin in rats with STZ-induced type 2 diabetes led to a notable enhancement in insulin sensitivity as compared to the control group." (PMID 37959677, 2023). "An updated literature search 28th of January 2022 did not identify any additional randomised clinical trials evaluating the effects of adding metformin to insulin in people with type 2 diabetes." (PMID 36923108, 2023). "Type 2 diabetes is metabolic disease that affects more than 90% of diabetic patients and is characterized by abnormally high blood sugar levels and insulin resistance in target organs such as adipose tissues, liver, and skeletal muscle." (PMID 37374154, 2023). "Evidence relative to the efficacy of isCGM in improving glycemic outcomes, including a greater TIR, a lower TBR, and a higher reduction in HbA1c levels, are also emerging among non-insulin-treated people with type 2 diabetes." (PMID 37676398, 2023). "Type 2 diabetes can enhance neurodegeneration through reduced brain insulin signaling, which can be more facilitated in patients with a lower BMI." (PMID 37719757, 2023). "The dysfunction and death of insulin-producing pancreatic β cells are key elements in the pathogenesis of type 1 and type 2 diabetes." (PMID 36652148, 2023). "Over time this leads to islet beta cell failure with reducing ability to produce enough insulin to assure glucose homeostasis, followed by fasting hyperglycemia and progressing to glucose intolerance and then to type 2 diabetes." (PMID 37189612, 2023). "The possibility of developing oral insulin formulations for the treatment of type 1 and type 2 diabetes continues to be explored." (PMID 36976228, 2023). "Imeglimin is a novel agent currently in development to treat type 2 diabetes and has also been shown to normalize glucose tolerance and improve insulin sensitivity by protecting mitochondrial function from oxidative stress." (PMID 37237539, 2023). "In type 2 diabetes, an increase in the blood insulin and HbA1c content and long-term hyperglycemia is generally observed." (PMID 37110159, 2023). "There are associations between cholesterol accumulation and pancreatic β-cell dysfunction, with individuals with type 2 diabetes exhibiting lipid abnormalities, which contribute to cholesterol accumulation in the cells and influence insulin secretion." (PMID 37999402, 2023). "PPARγ agonists (thiazolidinediones) improve insulin sensitivity and are used in the therapy of Type 2 diabetes." (PMID 36768666, 2023). "The safety of lixisenatide, a glucagon-like peptide-1 (GLP-1) receptor agonist, and sulfonylurea, when combined with basal insulin therapy, was examined in the LixiRam trial on people with type 2 diabetes who prefer to fast throughout Ramadan." (PMID 38169925, 2023). "Patients who have Type 2 diabetes face a higher risk of developing NAFLD, as both conditions share the feature of compromised insulin signaling." (PMID 38023570, 2023). "Altered insulin signalling can ultimately lead to insulin resistance, hyperglycaemia, and type 2 diabetes (T2D)." (PMID 37531359, 2023). "Our results indicate that inhibiting MCP-1 signaling in type 2 diabetic mice can partially restore proliferation and insulin secretion of the islet beta-cells." (PMID 37957155, 2023). "High expression of UQCRC1 leads to mitochondrial dysfunction and reduced ATP utilization, thereby accelerating the process of lipid deposition and insulin resistance in skeletal muscle, ultimately leading to the development of type 2 diabetes and obesity." (PMID 36782329, 2023). "In pancreatic β-cells, mitochondrial activity is essential for glucose-stimulated insulin secretion and mitochondrial dysfunction to the pathophysiology of type 2 diabetes." (PMID 37569434, 2023).
type 2 diabetes (continued). "Insulin and C-peptide levels were measured at plasma glucose concentrations of ~11 mmol/l in a small number of individuals with type 2 diabetes and at plasma glucose concentrations of ~5 mmol/l in healthy individuals." (PMID 37430117, 2023). "Overall, fifty-five (74.3%) patients of the with-HF group were over 65 years old, and 54 (73.0%) had a history of type 2 diabetes, with 50 (67.6%) patients taking oral antidiabetics or insulin." (PMID 37034347, 2023). "A meta-analysis demonstrated significant differences in glycemic and insulin reductions between different intensity subgroups in patients with type 2 diabetes after a period of resistance training." (PMID 36767015, 2023). "Adipocyte-derived hormones, including adiponectin and leptin, increase insulin sensitivity, a vital step in the aetiology of type 2 diabetes." (PMID 36826001, 2023). "ER stress induces pancreatic β-cell apoptosis, decreasing the number of cells and insulin secretion, which further progress type 2 diabetes." (PMID 38249612, 2023). "In contrast to the peripheral cell resistance of endogenous insulin in type 2 diabetes, T1D is mainly the consequence of autoimmune disease, leading to the destruction of the β-cells that produce insulin." (PMID 37400916, 2023). "Dietary and physical activity adjustments, oral hypoglycemic medications, and/or subcutaneous insulin injections are the gold standard for treating type 2 diabetes." (PMID 37371950, 2023). "They assessed omentin concentrations in obese individuals diagnosed with type 2 diabetes before the introduction of insulin treatment and after six months of therapy." (PMID 36830868, 2023). "Meanwhile, miR-146b and miR-15b play roles in inhibiting pancreatic insulin secretion induced by high glucose concentrations, contributing to the pathological processes of obesity and type 2 diabetes." (PMID 37904219, 2023). "Increased circulating levels of incompletely processed insulin (i.e. proinsulin) are observed clinically in type 1 and type 2 diabetes." (PMID 37537395, 2023). "infused SHED in type 2 diabetes patients receiving insulin, and the outcomes demonstrated that SHED infusion is a secure and reliable treatment that enhances islet function and glucose metabolism in type 2 diabetes patients." (PMID 38077342, 2023). "Type-2-diabetes arise due to constant intake of high glucose or sometimes due to degradation of insulin producing pancreatic cells." (PMID 36934168, 2023). "Type 2 diabetes mellitus (T2DM) is a chronic multisystem disease characterized by reduced peripheral tissue sensitivity to insulin (insulin resistance) and/or relative pancreatic β-cell dysfunction." (PMID 37376118, 2023). "The glucoregulatory actions of GLP-1RAs are well known and include glucose-dependent stimulation of insulin secretion and inhibition of glucagon release, resulting in a marked reduction in HbA1c in people with type 2 diabetes." (PMID 37542009, 2023). "Diabetic disorders such as type 2 diabetes (T2D) are driven by metabolic abnormalities connected to obesity and impaired insulin response, together with the rise of hepatic glucose production, thus ultimately disrupting glucose homeostasis." (PMID 37298872, 2023). "The treatment of type 2 diabetes involves stimulating and increasing endogenous insulin production or inhibiting the digestive enzymes α-amylase and α-glucosidase." (PMID 37999402, 2023). "A recent study supported these results and concluded that nocturnal hypoglycaemia is very common and largely underdiagnosed in older people with insulin-treated type 2 diabetes." (PMID 37817166, 2023). "The Spontaneously Diabetic Torii (SDT) rat model is based on the principle that deformation of pancreatic beta‐cells leads to impaired insulin secretion, resulting in the development of a type 2 diabetes‐like phenotype." (PMID 37723622, 2023). "Rosiglitazone and pioglitazone, which are PPARγ agonists, are shown to increase insulin sensitivity and are used to treat type 2 diabetes." (PMID 37626963, 2023).
type 2 diabetes (continued). "The available evidence relates higher asprosin plasma levels with impaired insulin sensitivity in the case of gestational diabetes mellitus, type 2 diabetes, and PCOS." (PMID 36615188, 2023). "For example, insulin or an insulin pen is required for insulin-dependent patients to prevent short-term complications (e.g., coma due to hyperglycemia) and long-term complications (e.g., renal failure or blindness) or early death." (PMID 37228726, 2023). "Here, we demonstrate that this technology can benefit the wider population with type 2 diabetes requiring insulin and can be safely implemented in the home setting." (PMID 36631592, 2023). "Similar efficacy and safety of icodec to once-daily basal insulin analogues have been reported in over 4,200 participants with type 2 diabetes from three phase II and five phase III trials." (PMID 37313230, 2023). "Other pathways relevant to insulin and circadian signaling were also identified, such as an onset of type 2 diabetes and circadian clock." (PMID 36551676, 2022). "Type 2 diabetes is characterized by impairment in insulin secretion, with an established genetic contribution." (PMID 35163144, 2022). "In vivo studies have shown that gymnemic acids increase insulin secretion by enhancing beta cells membrane insulin permeability, decrease blood glucose levels in patients with type 2 diabetes, and protect β cells against oxidative stress." (PMID 36297570, 2022). "The current OCTA study focused on type 2 diabetic patients and aimed to study how their retinal microvasculature networks responded to intensive insulin therapy, compared with the oral hypoglycemic agent group." (PMID 35459162, 2022). "The fact that 13-a-OH lupanine and 17-oxo-lupanine stimulate insulin secretion only at high glucose concentrations indicates that it would reduce the risk of hypoglycemia which could be of additional value when considering their potential use in the treatment of type 2 diabetes." (PMID 35282429, 2022). "The efficacy of 400 mg/kg of TME of B. eriophora in controlling the blood glucose level in STZ- and HFD-induced diabetic rats was better than GLB, an insulin secretagogue employed in type 2 diabetic patients." (PMID 36296534, 2022). "Especially when serum insulin levels are high, as in obese patients with type 2 diabetes, IGF-1 (insulin-like growth factor) receptors are now thought to mediate main proliferative effects." (PMID 36291064, 2022). "At present, there are few literature studies on the treatment of type 2 diabetes with glimepiride combined with recombinant human insulin injection." (PMID 35571731, 2022). "We collected retrospective CGMs data from 2,600 patients with type 2 diabetes with stable treatment of insulin." (PMID 36237834, 2022). "In individuals with adult-onset diabetes, the presence of N-terminally truncated GAD65 autoantibodies is associated with the clinical phenotype of autoimmune T1D and predicts insulin therapy." (PMID 36090989, 2022). "Type 2 diabetes results from impaired insulin secretion, insulin resistance or a combination of both." (PMID 35421974, 2022). "A recent study reported that in a type 2 diabetes mouse model, which cannot be controlled by metformin alone, additional vitamin D therapy improved insulin sensitivity in skeletal muscles." (PMID 35265081, 2022). "Insulin degradation was not a popular subject during Mirsky’s time, as the discovery of the radioimmunoassay by Yalow and Berson had focused attention on insulin secretory dysfunction as a very important factor in the pathogenesis of type 2 diabetes." (PMID 35163746, 2022). "Others were associated with glycemic or insulinemic traits, including fasting glucose, glycated hemoglobin, fasting insulin, or type 2 diabetes." (PMID 35464866, 2022). "PEA was also well tolerated and reported to be safe as an adjunct in patients prescribed metformin and or insulin for the management of either type 1 or type 2 diabetes." (PMID 36057884, 2022).